CEP55 (centrosomal protein 55)
Diseases named in the same sentence as CEP55 in open-access papers (continued):
Sharing a sentence is not in itself a finding about the gene and the disease.
ovarian carcinoma (continued). "Interestingly, ovarian cancer patients in our study with aberrant CEP55 protein expression had a tendency to accept neoadjuvant chemotherapy." (PMID 26615423, 2016). "However, a significant correlation was found between higher CEP55 expression and shorter OS in the HIPEC subgroup, which indicates that CEP55 expression is an important prognostic factor of ovarian cancer patients who accept HIPEC." (PMID 26615423, 2016). "Furthermore, we analyzed the correlation between CEP55 expression and the clinicopathological features of ovarian cancer patients." (PMID 26615423, 2016). "Taken together, our results suggest that CEP55 may be a marker predicting unfavorable outcomes in ovarian carcinoma and plays a significant role in the migration and invasion of human EOC." (PMID 26615423, 2016). "However, further studies are required to obtain a detailed picture of CEP55-related signaling pathways in regulating ovarian cancer EMT." (PMID 26615423, 2016). "Interestingly, Western blot analysis showed that CEP55 protein expression levels were positively correlated with clinical stages of ovarian carcinoma patients." (PMID 26615423, 2016). "Additionally, downregulation of CEP55 in ovarian cancer cells remarkably inhibited cellular motility and invasion." (PMID 26615423, 2016). "In order to determine whether the CEP55 upregulation found in ovarian cancer cell lines was related to clinical biochemical indicators, we did Western blotting analysis on 12 paired epithelial ovarian carcinoma tissues and noncancerous tissues adjacent to ovarian tumors." (PMID 26615423, 2016). "Moreover, we observed a significant correlation between shorter OS and high CEP55 protein expression in the subgroup with intraperitoneal metastasis, which indicates that CEP55 may be a useful prognostic marker for such ovarian cancer patients." (PMID 26615423, 2016). "However, characteristics of CEP55 expression and its clinical/prognostic significance in human ovarian cancer remain unknown." (PMID 26615423, 2016). "Eight genes (NUF2, GTSE1, DEPDC1, KIF18B, PBK, CEP55, HJURP, SKA1) were potential hub genes correlated to ovarian cancer progression." (PMID 35173547, 2022). "Moreover, CEP55 may induce ovarian cancer lymph node metastasis through regulating EMT." (PMID 26615423, 2016). "CEP55 overexpression increases tumorgenicity in gastric carcinoma, while high expression of CENP-A correlates with poor survival in epithelial ovarian cancer." (PMID 26121572, 2015). "Additionally, the CEP55 protein expression was generally weak in early stage ovarian cancer (FIGO stages I and II), while it was strong in later stage ovarian cancer (FIGO stages III and IV) tissues." (PMID 26615423, 2016). "Aberrant CEP55 expression may predict unfavorable clinical outcomes in EOC patients and play an important role in regulating invasion in ovarian cancer cells." (PMID 26615423, 2016). "In addition, multivariate Cox regression analysis revealed that CEP55 protein level, lymph node metastasis, intraperitoneal metastasis, FIGO stage, recurrence, age, and neoadjuvant chemotherapy were indeed independent prognostic markers for ovarian cancer." (PMID 26615423, 2016). "We found that both CEP55 mRNA and protein showed aberrant expression levels in ovarian cancer tissues compared with noncancerous tissues, indicating that the overexpression of CEP55 occurred not only at the posttranscriptional level but also at the transcriptional level." (PMID 26615423, 2016).
colon carcinoma (13 papers, 2016 to 2025). "The elevated CEP55 messenger RNA (mRNA) was observed in CRC tissues using RT‐PCR in an OriGene Colon Cancer cDNA array." (PMID 33190424, 2021). "For example, CEP55 was demonstrated to be highly expressed in colon carcinoma, oral cavity squamous cell carcinoma, and bladder transitional cell carcinoma." (PMID 27357513, 2016). "High expression of CEP55 has been demonstrated to be involved in Fn-infected colon cancer cell growth and cell cycle progression, and could be used as a new diagnostic and prognostic biomarker for Fn-infected CRC." (PMID 34650590, 2021). "Our findings suggest that CEP55 plays an important role in Fn-infected colon cancer cell growth and cell cycle progression and could be used as a new diagnostic and prognostic biomarker for Fn-infected CRC." (PMID 34650590, 2021). "Our results further suggested that CEP55 might play an important role in Fn-infected colon cancer cell growth and cell cycle progression." (PMID 34650590, 2021). "Therefore, we speculated that high CEP55 expression might affect Fn-infected colon cancer cells proliferation and differentiation through mitotic nuclear division, cytokinetic process and immune infiltration." (PMID 34650590, 2021). "We found that CEP55 is significantly expressed in CRC (including rectal cancer and colon cancer) in the NGS data of Oncomine and TCGA (p < .05)." (PMID 33190424, 2021). "Moreover, the expression level of CEP55 was significantly increased in Fn-infected CRC, and knockdown of CEP55 suppressed Fn-infected colon cancer cell growth by impairing cell cycle and apoptosis progression." (PMID 34650590, 2021).
colorectal cancer (12 papers, 2018 to 2025). A primary or metastatic malignant neoplasm that affects the colon or rectum. "Notably, a CEP55 peptide vaccine was proposed for breast and colorectal carcinoma immunotherapy as CEP55 is involved in the PI3K/Akt signaling pathway." (PMID 39450169, 2024). "Ultimately, experimental validation through quantitative PCR in gastric and colorectal cancer tissue specimens confirmed that the transcript levels of AURKA, CEP55, DTL, and TTK are markedly elevated in tumor tissues compared to normal tissues." (PMID 40723362, 2025).
gastric cancer (12 papers, 2015 to 2023). A primary or metastatic malignant neoplasm involving the stomach. "On the other hand, the overexpression of some hub genes such as centrosomal protein 55 (cep55), centrosome-associated protein E (cenpe), and epithelial cell transforming 2 (ect2) indicated a positive effect on the survival of gastric cancer cases." (PMID 35650297, 2022). "CEP55 knockdown arrests the cell cycle at the G2/M phase and suppresses gastric cancer cell expansion." (PMID 37484531, 2023). "Interestingly, in this analysis, cep55 overexpression was found to relate to a positive prognosis in gastric cancer patients." (PMID 35650297, 2022). "CEP55 enhances cell growth, and its knockdown inhibits cell growth in breast and gastric cancers." (PMID 34070979, 2021). "Moreover the overexpression of two other paired genes, i.e. (cep55, cenpe) and (cep55, ect2), revealed a good impact on survival, so that using their agonist may have a synergistic effect on gastric cancer survival." (PMID 35650297, 2022). "CEP55 upregulation was correlated with the improved phosphorylation of AKT, which finally promoted cell proliferation in gastric carcinoma." (PMID 37175004, 2023). "Compared with normal tissues, ADAM12, CEP55, LRFN4, and INHBA were up-regulated in gastric cancer samples, while ADH1B, DPT, FAM107A, and LOC100506388 were downregulated." (PMID 34686626, 2021).
glioma (11 papers, 2019 to 2025). A benign or malignant brain and spinal cord tumor that arises from glial cells (astrocytes, oligodendrocytes, ependymal cells). "A previously published study reported that CEP55 is highly expressed in the glioma tissue and that overexpression of CEP55 promoted glioma cells’ proliferation and inhibited its apoptosis by activating the PI3K/Akt pathway." (PMID 40504854, 2025). "The expression level of CEP55 protein in glioma tissues was significantly higher than that in normal control group, and the expression level in glioma tissues increased with the increase of glioma grade 17." (PMID 40386043, 2025). "CEP55 expression is increased in human glioma tissues and cell lines compared with normal brain tissue and cells, and high CEP55 expression in glioma is related to poor prognosis." (PMID 34944109, 2021). "Although there are reports of a relationship between SHCBP1 and CEP55 in glioma, these have only focused on their roles in the migration and invasion of glioma cells." (PMID 32351983, 2020). "Regarding tumor development, CEP55 is involved in the development of glioma, hepatocellular carcinoma, breast cancer, lung cancer, and ovarian cancer." (PMID 32351983, 2020). "We used glioma lncRNA and mRNA databases to analyze the role of SHCBP1 and CEP55 in glioma and their associations with prognosis." (PMID 32351983, 2020). "This work demonstrated that overexpression of CEP55 might enhance the invasion and migration in the glioma tissue." (PMID 40504854, 2025). "Given that AURKA has been proposed as a potential therapeutic target in glioblastoma, these findings suggest that inhibition of CEP55–AURKA signaling could be a novel strategy for the treatment of glioma and glioblastoma." (PMID 34944109, 2021). "For example, CEP55 promoted the migration, invasion, and neurosphere formation of the glioma cell, promoted epithelial-mesenchymal transition in renal cell carcinoma through the PI3K/AKT/mTOR pathway, and promoted migration and invasion of esophageal squamous cell carcinoma via the PI3K/AKT pathway." (PMID 34055036, 2021). "CEP55 has been found to promote cell proliferation and inhibits cell apoptosis in glioma." (PMID 32047515, 2019). "In conclusion, we found that CEP55 and SHCBP1 can be used to predict the prognosis of glioma patients with high accuracy and that SHCBP1 is an independent prognostic factor for glioma patients." (PMID 32351983, 2020). "We further analyzed CEP55 and SHCBP1 expression in gliomas, their relationships to patient prognosis, and their enriched KEGG signaling pathways." (PMID 32351983, 2020). "Additionally, CEP55 and SHCBP1 were highly expressed in glioma specimens and showed increased expression according to the glioma grade, and outcomes of high expression patients were poor." (PMID 32351983, 2020). "To determine the role of CEP55 and SHCBP1 in glioma, we performed KEGG analyses." (PMID 32351983, 2020). "Furthermore, CEP55 and SHCBP1 were highly expressed in gliomas, showing higher expression in higher grade cases, and high expression patients had poorer prognoses." (PMID 32351983, 2020).
pancreatic cancer (11 papers, 2017 to 2025). "CEP55 is upregulated in pancreatic cancer and is associated with poor survival." (PMID 31612115, 2019). "In vitro knockdown of CEP55 effectively suppressed proliferation and invasion capabilities in pancreatic cancer cell lines." (PMID 40677006, 2025). "In some cancers, such as non-small cell lung cancer 27, pancreatic cancer 28, renal cell carcinoma 29, and T cell lymphoma 30, CEP55 is often highly expressed and promotes tumor development, thereby becoming an effective diagnostic marker." (PMID 40386043, 2025). "CEP55 can also promote aggressive behavior in pancreatic cancer cells by activating the NF-κB pathway." (PMID 32587798, 2020). "In the Grutzmann Pancreas dataset, CDK1 and CEP55 mRNA expression was higher in pancreatic cancer tissues than in normal pancreatic tissues." (PMID 32587798, 2020). "Oncomine analysis of cancer vs. normal tissue indicated that CDK1 and CEP55 were significantly overexpressed in pancreatic cancer in different datasets." (PMID 32587798, 2020). "The results showed that CDK1 and CEP55 were significantly overexpressed in pancreatic tumorous tissues compared to normal tissues, which is consistent with the results in different datasets." (PMID 32587798, 2020). "CEP55 promotes pancreatic cancer proliferation, migration, and invasion in vitro and in vivo by activating the NF-κB signaling pathway and the PI3K/AKT signaling pathway." (PMID 31612115, 2019). "To explore the expression of the CEP55 gene and its clinical significance in human PANC, first, we analysed CEP55 mRNA expression in primary pancreatic tumours from publicly available PANC datasets (TCGA and GSE71729)." (PMID 28724890, 2017). "Also, CEP55 upregulation promotes PANC cell aggressiveness via activating pancreatic cancer." (PMID 33386701, 2021). "However, the role of CEP55 in pancreatic cancer (PANC) remains unclear." (PMID 28724890, 2017). "Last, we preliminarily validated the ChIP analyses by detecting CDK1 and CEP55 protein levels in eight snap-frozen tumorous and adjacent noncancerous adjacent tissues of pancreatic cancer patients." (PMID 32587798, 2020). "In the clinical specimens, CDK1 and CEP55 protein levels were significantly elevated in pancreatic cancer tissue samples compared with adjacent nontumor tissues." (PMID 32587798, 2020). "Immunohistochemical results showed that among the 8 CRGs: CEP55, FAM111B, MRPL3, MET, and KNSTRN had higher protein expression in pancreatic cancer tissues, while on the contrary, the protein expression of DHX30 in normal pancreas was significantly higher than that in pancreatic cancer tissues." (PMID 40677006, 2025). "Nonetheless, the relationship between CEP55 and CDK1 and the mechanism involved have not been studied in pancreatic cancer cells." (PMID 32587798, 2020). "Lastly, the eight snap-frozen tumorous and adjacent noncancerous adjacent tissues of pancreatic cancer patients used to detect the CDK1 and CEP55 protein levels by western blot." (PMID 32587798, 2020).
osteosarcoma (10 papers, 2017 to 2024). A usually aggressive malignant bone-forming mesenchymal neoplasm, predominantly affecting adolescents and young adults. "As a centrosomal protein, CEP55 (centrosomal protein 55) is a key regulator of cytokinesis and promotes osteosarcoma malignancy through the AKT pathway." (PMID 38254188, 2024). "For instance, CEP55, highly expressed in osteosarcoma, facilitates the proliferation and invasion of tumor cells by activating AKT signaling." (PMID 35037833, 2022). "CEP55 promotes the proliferation and invasion of osteosarcoma cells through the AKT signaling pathway." (PMID 35028418, 2022). "CEP55 knockdown significantly induces cell cycle arrest at G1 phase, suppresses osteosarcoma cell proliferation in vitro through regulating the PI3K/AKT pathway, and suppresses osteosarcoma tumor growth in mice." (PMID 33497018, 2021). "In addition, CEP55 is overexpressed in human osteosarcoma tissues, and its overexpression correlates with poor patient prognosis." (PMID 33497018, 2021). "It was reported that CEP55 could promote proliferation and invasion in the progress of osteosarcoma." (PMID 34093635, 2021). "Furthermore, CEP55 was shown to activate CCND1 and FN1 via the AKT signaling pathway, thereby regulating the proliferation and invasion of osteosarcoma cells." (PMID 32149111, 2020).
esophageal squamous cell carcinoma (9 papers, 2020 to 2024). Esophageal squamous cell carcinoma (ESCC) is a type of esophageal carcinoma (EC) that can affect any part of the esophagus, but is usually located in the upper or middle third. "After validation using survival analysis and dry-lab and wet-lab-based studies, we identified the I-miR-378-5p-APOC1/CEP55 as a critical pathway for esophageal squamous cell carcinoma progression after neoadjuvant immunotherapy." (PMID 38172247, 2024). "By combining expression analysis, survival analysis, and wet and dry research validation, a key pathway (hsa-miR-378-5p-APOC1/CEP55) of esophageal squamous cell carcinoma progression after neoadjuvant immunotherapy was identified." (PMID 38172247, 2024). "Two key mRNAs related to esophageal squamous cell carcinoma, APOC1 and CEP55, and miRNAs closely associated with them, including hsa-miR-378a, hsa-miR-145, and hsa-miR-504, were identified using expression and survival analyses." (PMID 38172247, 2024). "Immune infiltration analysis demonstrated that the expression of APOC1 and CEP55, the purity of esophageal squamous cell carcinoma cells, and numerous immune infiltration cells were closely related." (PMID 38172247, 2024). "Another study proposed that CEP55 promotes the proliferation, migration, and invasion of esophageal squamous cell carcinoma via the PI3K/Akt pathway." (PMID 38172247, 2024). "This pathway demonstrates that miR-378a-5p acts as an active tumor suppressor by targeting and regulating APOC1 and CEP55 during the onset and progression of esophageal squamous cell carcinoma." (PMID 38172247, 2024). "The results demonstrated that the expression of APOC1 and CEP55 and the purity of esophageal squamous cell carcinoma cells were correlated (p < 0.05)." (PMID 38172247, 2024). "The analysis showed that APOC1 and CEP55 were significantly upregulated in esophageal squamous cell carcinoma tissues, which was consistent with our analysis results." (PMID 38172247, 2024). "Overexpression of CEP55 was found to promote proliferation, metastasis and invasion of esophageal squamous cell carcinoma by activating PI3K/Akt signaling pathway." (PMID 34650590, 2021). "Subsequently, when we performed PCR validation on surgical specimens after neoadjuvant immunotherapy, we found that APOC1 and CEP55 were significantly upregulated and hsa-miR-378a-5p and hsa-miR-378a-3p were considerably downregulated in esophageal squamous cell carcinoma samples." (PMID 38172247, 2024). "Thus, CEP55 could be another decent target for efficacy prediction after neoadjuvant immunotherapy of esophageal squamous cell carcinoma." (PMID 38172247, 2024). "Typically, CEP55 is expressed during embryogenesis and is silent in adult tissues except in the testis and thymus; however, the overexpression of CEP55 has been reported in multiple cancer types, including breast, non-small cell lung, prostate, and esophageal squamous cell carcinoma." (PMID 38250876, 2024). "Additionally, the researchers implied that CEP55 positively influenced the tumorigenesis of esophageal squamous cell carcinoma by enhancing the colony formation and migration of ESCC cells through the phosphorylation of Src, FAK, and ERK." (PMID 37274251, 2023).
non-small cell lung carcinoma (9 papers, 2020 to 2025). A group of at least three distinct histological types of lung cancer, including non-small cell squamous cell carcinoma, adenocarcinoma, and large cell carcinoma. "Another study found that inhibiting miR-144-3p accelerates the growth of non-small cell lung cancer by targeting CEP55." (PMID 35501800, 2022).
oral cavity squamous cell carcinoma (9 papers, 2015 to 2025). A squamous cell carcinoma arising from the oral cavity. "Furthermore, CEP55 drives the migration and invasion of oral cavity squamous cell carcinoma by increasing FOXM1 and MMP-2 activity." (PMID 37484531, 2023). "In addition, expression of CEP55 was correlated with aggressiveness of oral cavity squamous cell carcinoma by stimulating cell migration and invasion through increased FOXM1 and MMP-2 activity." (PMID 26615423, 2016).
lung adenocarcinoma (8 papers, 2009 to 2025). A carcinoma that arises from the lung and is characterized by the presence of malignant glandular epithelial cells. "LINC01667 can act as a sponge to regulate genes such as CCNB1, CEP55, MKI67, and TYMS, and ultimately affect the progression of lung adenocarcinoma." (PMID 34458133, 2021).